NF1P1 (neurofibromin 1 pseudogene 1)
Synonyms: NF1HHS
Gene: Transcribed unprocessed pseudogene on chromosome 15 (20,916,686 to 20,935,658, reverse strand). Ensembl gene ENSG00000270831.
Diseases named in the same sentence as NF1P1 in open-access papers:
NF1P1 is named in the same sentence as 1 disease in open-access papers, as found by Europe PMC text mining. Sharing a sentence is not in itself a finding about the gene and the disease. The quoted sentences say what the papers report.
Arrhythmia (1 paper, 2015). Any cardiac rhythm other than the normal sinus rhythm. "The partial reduction in ALK function throughout development did not cause arrhythmia nor did it suppress arrhythmia in Nf1P1/P2 flies." (PMID 26536237, 2015).